IL22 (interleukin 22)
Diseases named in the same sentence as IL22 in open-access papers (continued):
Sharing a sentence is not in itself a finding about the gene and the disease.
inflammatory bowel disease (continued). "Furthermore, recent evidence suggests that the NLRP3 inflammasome and its maturation of IL-18 downregulates the IL-22 binding protein, an inhibitor of IL-22, which promotes cell repair in inflammatory bowel diseases." (PMID 24312491, 2013). "However, within disorders such as inflammatory bowel disease (IBD), IL-22 played either protective or pathogenic role in discrepant induction by naive and memory/effector cells." (PMID 23236476, 2012). "IL-17 and IL-22 producing human ILCs are responsive to IL-23 signaling and could be important mediators of inflammatory bowel diseases." (PMID 22829946, 2012). "In inflammatory bowel disease, high levels of IL-22 are present in inflamed tissue." (PMID 22346753, 2012). "Consequently, both IL-17 and IL-22 may contribute to the development of autoimmune diseases, such as rheumatoid arthritis, inflammatory bowel disease and, as observed in our study, in CD." (PMID 38255930, 2024). "Different forms of IL-22 are progressing to clinical trials for inflammatory bowel disease (IBD) and have demonstrated significant anti-inflammatory effects." (PMID 37695525, 2023). "IL-22 exerts antiviral properties against COVID-19 and influenza, as well as beneficial action in inflammatory bowel disease (IBD)." (PMID 37628830, 2023). "These cells serve as the primary source of IL-22, and both Th22 cells and IL-22 are believed to play a role in maintaining intestinal mucosal homeostasis in inflammatory bowel disease (IBD)." (PMID 37646028, 2023). "The high expression of IL-22 might inhibit the development of inflammatory bowel disease (IBD)." (PMID 35523778, 2022). "During inflammatory bowel disease (IBD), immune cells upregulate the secretion of IL-17, IL-21, IL-22, and IL-23 cytokines in the intestinal mucosa." (PMID 34207946, 2021). "The IL-20 cytokines IL-19, IL-20, IL-22, IL-24, and IL-26 are elevated in autoimmune/inflammatory diseases, such as in the skin of patients with psoriasis, in synovial fibroblasts, and macrophages of patients with rheumatoid arthritis and in patients with inflammatory bowel disease." (PMID 29967613, 2018). "It has been previously reported that IL-22, one of the cytokines secreted by Th17 cells, demonstrates both a protective and inflammatory promotion effect in inflammatory bowel disease (IBD) through STAT3 signaling activation." (PMID 23379788, 2013). "In 5-Tm, GOs including Th17 differentiation pathway, inflammatory bowel disease, and allograft rejection, represented by IL12RB1, IRF4, LAT, and IL22, were observed in PE." (PMID 38774869, 2024). "While IL-10 is known to be anti-inflammatory, IL-22 fulfills a proinflammatory role in many different tissues and is involved in numerous diseases, including inflammatory bowel disease (IBD), psoriasis, and cancer, making it an interesting target or potential therapeutic." (PMID 39447666, 2024). "During inflammatory tissue damage, such as inflammatory bowel disease or graft-versus-host disease (GVHD), IL-22 is important for maintaining intestinal epithelial integrity by inducing epithelial cell proliferation and intestinal stem cell differentiation." (PMID 39253083, 2024). "A novel lipid nanoparticle (nLNP), formulated with three essential lipids to mimic ginger-derived exosomal particles, shows strong potential for delivering IL-22 mRNA specifically to the colon, presenting a unique oral drug delivery system for inflammatory bowel disease (IBD)." (PMID 39591041, 2024). "KEGG pathway analyses showed that VD-R and IL-22 mRNA were mainly concentrated in multiple signal transduction pathways such as the JAK/STAT signaling pathway in tuberculosis, prostate cancer, and inflammatory bowel disease." (PMID 34917427, 2021).
inflammatory bowel disease (continued). "Additionally, the delivery of IL-22 has shown beneficial effects in the pathology of several animal models of disease including vancomycin resistant enterococcus infections, liver damage, diabetic wounds and inflammatory bowel disease, thus demonstrating its therapeutic potential." (PMID 32582668, 2020). "In a model of inflammatory bowel disease, CD4 T cells strongly expressed the IL-22 reporter in mesenteric lymph node." (PMID 26834739, 2015). "Furthermore, patients suffering from inflammatory bowel disease (IBD) revealed enhanced numbers of ILCs expressing IL-17 and IL-22." (PMID 24987710, 2014). "Besides being highly expressed in pancreatic tissue, Reg proteins were also found to be inducible in the intestinal tract, particularly Reg1 and Reg3 subfamily proteins that were induced by IL6/IL22 in inflammatory bowel disease (IBD) for mucosal regeneration through STAT3 activation." (PMID 39857608, 2024). "The seRNAs IFNG-r-49 regulates the expression of IL-26 and IL-22 in inflammatory bowel disease (IBD), but does not regulate the expression of IFNG." (PMID 36726725, 2023). "Collectively, their findings suggest that the new proliferative factor REG1A, which is regulated by IL-6/IL-22-JAK-STAT3 signaling, may represent an attractive therapeutic target for patients with inflammatory bowel disease." (PMID 35432477, 2022). "The discussion as to whether increased IL22 levels play a beneficial role, by promoting epithelial regeneration, or contribute to the development of chronic inflammation in inflammatory bowel diseases (IBD) is ongoing." (PMID 33266022, 2020). "Thus, IL-22 is an attractive and promising target for inflammatory bowel disease (IBD) therapy." (PMID 28830549, 2017). "Among these cytokines, IL-22 has been of specific interest because it is released by CD4+ Th17 T cells in diseases such as hepatitis and inflammatory bowel disease, where IL-22 expression levels have been shown to promote cell regeneration and survival in hepatocytes and colonal epithelial cells." (PMID 25408874, 2013). "In humans STAT3 represents one of the disease loci for Crohn's and inflammatory bowel disease (IBD), and most likely relates to the capacity of Stat3 to promote intestinal barrier function and integrity in response to IL6, IL11 and IL22 exposure." (PMID 20478049, 2010). "In inflammatory bowel diseases (IBD), a decreased frequency of MAIT cells in peripheral blood and an increased number in intestinal tissue were observed, and the production of IL-17 and IL-22 by MAIT cells was increased." (PMID 33777009, 2021).
autoimmune disease (116 papers, 2008 to 2026). A disorder resulting from loss of function or tissue destruction of an organ or multiple organs, arising from humoral or cellular immune responses of the individual to their own tissue constituents. "It is evident that MAIT cells play a critical role in maintaining intestinal barrier integrity through their production of IL-17 and IL-22, and disruption of this function is linked to autoimmune diseases, including T1D." (PMID 40607421, 2025). "Interleukin 22 (IL-22), a member of the IL-10 cytokine family, is closely associated with various chronic inflammatory diseases and autoimmune diseases." (PMID 38791032, 2024). "Th22 cells, a new type of characterized CD4 + T cells with IL22 as the main cytokines, are associated with the pathogenesis of autoimmune diseases." (PMID 35756043, 2022). "Th22/IL-22 plays a pathogenic role in most autoimmune diseases, while IL-22 has been shown to have a protective effect in many other diseases involving skin and mucosal barrier." (PMID 34295334, 2021). "IL-22 plays a key role in mucosal barrier defense, tissue repair, survival, and proliferation of epithelial cells, but evidence demonstrated both the protective and the pathogenic properties of IL-22 in autoimmune disease, infection, and malignancy." (PMID 33344684, 2020). "Researches have demonstrated that Th22 cells, by producing pro-inflammatory cytokines such as IL-22, were implicated in the pathogenesis of various inflammatory diseases and autoimmune diseases." (PMID 31501353, 2019). "IL-22 is an inflammatory cytokine that promotes inflammation and is associated with autoimmune diseases." (PMID 30984205, 2019). "Dysregulation of interleukin-22 (IL-22) has been associated with autoimmune diseases but divergent effects upon inflammation have hampered efforts to define its contribution to pathogenesis." (PMID 29163483, 2017). "Th17 cells, specifically implicated in autoimmune diseases including type 1 diabetes, can secrete IL-22 and IL-17A, which has been identified as a factor promoting the pro-inflammatory effect of IL-22." (PMID 26751709, 2016). "Thereby, Th22 cells and in particular IL-22 are implicated as a potential therapeutic target in autoimmune diseases." (PMID 27651750, 2016). "The IL-17- and IL-22-producing Th17 cells contribute to the host defense against extracellular pathogens, and they are implicated in the pathogenesis of autoimmune disorders." (PMID 24527450, 2014). "Th17 cells, which are a subset of effector CD4+ T cells specialized in the production of IL-17 and IL-22 and in recruitment and activation of neutrophils, have been implicated in autoimmune diseases, including multiple sclerosis, lupus and diabetes." (PMID 21494636, 2011). "Moreover, IL17A and IL22 are also known to mediate type 3 immunity and disruption in their function has been associated with various infectious diseases, autoimmune disorders, and cancer." (PMID 38993777, 2024). "Autoimmune disorders, chronic inflammatory illnesses, and neoplasms have been linked to the pathophysiology of inappropriate Th17 activity and excessive production of IL-17 A or IL-22." (PMID 38183030, 2024). "Recent studies show that Th22 cells, identified as a distinct subset of the Th cell family by specific production of IL-22, play crucial roles in regulating immune responses and are closely associated with multiple diseases, such as skin inflammation, infections, autoimmune diseases, and tumors." (PMID 28030850, 2017). "IL-22 and IL-17A are implicated in the pathogenesis of autoimmune diseases." (PMID 24404171, 2014). "Paradoxically, IL-22 has been shown to be pathogenically associated with several autoimmune diseases including rheumatoid arthritis and Crohn's disease as well as non-autoimmune diseases such as respiratory-distress syndrome and cystic fibrosis." (PMID 22164330, 2011).
autoimmune disease (continued). "This may help the body to create homeostasis in the microbiota, preventing chronic inflammation and the development of serious diseases because an imbalance in the concentration of IL-23, IL-22, and IL-17 cytokines observed in chronic inflammation is associated with autoimmune diseases and cancer." (PMID 38068860, 2023). "In addition, IL-22 induces the expression of proinflammatory cytokines that activate signal transducer and activator of transcription 3 (Stat3), which is associated with autoimmune diseases." (PMID 30159338, 2018). "Thus, as IL-23 promotes IL-22 responses, and because of the increasing recognition of pathogenic roles for IL-22 in autoimmune disorders 33,34 including SLE 35–38, we investigated whether IL-22 production in the kidney was associated with SLE pathogenesis." (PMID 25546822, 2015). "IL22 has been found to participate in the progression of various autoimmune diseases including aggravating lupus nephritis." (PMID 41155532, 2025). "Th17-related cytokines—interleukin (IL)-17, IL-21, and IL-22—play distinct and complementary roles in the pathogenesis of autoimmune diseases." (PMID 41035651, 2025). "Th17 cells are a subset of helper T cells that primarily secrete IL-17, IL-22, and other pro-inflammatory factors and play a significant role in autoimmune diseases." (PMID 41204487, 2025). "If so, it would be a beneficial phenomenon, distinguishing PA from other autoimmune diseases in which an increase in IL-17A (as well as in IL-22, IL-23) activity is observed." (PMID 37269464, 2023). "Increasing concentrations of TGF-β were found to inhibit IL-6-induced production of IL-22 in Th17 cells in a model of autoimmune disease." (PMID 38162671, 2023). "Interleukin-22 (IL-22) is a protective inflammation factor that plays a critical role in the pathogenesis of autoimmune diseases and anti-apoptosis." (PMID 37069575, 2023). "Recent studies have shown that IL-22 plays an important role in the pathogenesis of autoimmune diseases." (PMID 36986586, 2023). "Following the activation, Th17 cells produce IL-17 and IL-22 which contribute to the inflammatory response in autoimmune diseases." (PMID 35116069, 2022). "IL-22 is the source of increasing attention in a wide range of inflammatory and autoimmune diseases due to its specific function in vivo." (PMID 34917427, 2021). "IL-22, the main effector of Th22 cells,also exerts different functions in different autoimmune diseases." (PMID 34295334, 2021). "Previous investigations have shown a critical role of IL-22 during the pathogenesis of autoimmune diseases." (PMID 34295334, 2021). "Further investigations on the safety,tolerability and therapeutic effects of agents targeting Th22/IL22 pathway are needed for the effective treatment of autoimmune diseases." (PMID 34295334, 2021). "Studies have found that PGE2 participates in T helper 1 (Th1)-cell differentiation, Th17-cell expansion, and IL-22 secretion from Th22 cell to induce chronic inflammation and various autoimmune diseases." (PMID 34116703, 2021). "Lactobacilli can promote interleukin (IL)-22 secretion and prevent autoimmune diseases by stimulating the production of antimicrobial peptide and can reinforce the mononuclear phagocytic response." (PMID 34879874, 2021). "Here, we review research advances in the origin, characteristics and effector mechanisms of Th22 cells, with an emphasis on the role of Th22 cells and their main effector cytokine IL-22 in the pathogenesis of autoimmune diseases." (PMID 34295334, 2021). "The expression of AMPs, which include cathelicidins and defensins, can also promote IL-22 secretion and thus prevent autoimmune diseases." (PMID 32727366, 2020). "IL-22 plays an important role in immune responses, par ticularly in inflammatory and autoimmune diseases in humans and animals." (PMID 33344684, 2020).
autoimmune disease (continued). "Recently, Th17 related cytokines such as IL-1β, IL-6, IL-17, IL-21, IL-22, and IL-23 play crucial roles in the pathogenesis of many diseases, including inflammatory diseases, autoimmune diseases, and cancers." (PMID 32252668, 2020). "Therefore, the identification of stimulatory molecules and associated signaling pathways regulating and/or amplifying IL-22 production may provide new insight into immune defense against pathogens and novel therapeutic targets for inflammatory and autoimmune diseases." (PMID 33178223, 2020). "In contrast to infectious disease models, CS was found to enhance IL-22 and IL-17 responses in autoimmune diseases." (PMID 32189996, 2020). "Th17 cells are generally pro-inflammatory, acting via the release of mediators such as IL-17A and IL-22 and play an important role in autoimmune diseases (e.g., Crohn’s disease)." (PMID 33537029, 2020). "Interleukin 22 (IL22) is a cytokine either playing a protective or a pathological role in different autoimmune diseases." (PMID 30072615, 2018). "Previous studies have found that IL-22 plays differing roles in the pathogenesis of a number of autoimmune diseases." (PMID 30159338, 2018). "TH17 cells produce the effector cytokines IL-17A, IL-17F, IL-22, and GM-CSF to mediate pathological inflammation responsible for many types of autoimmune diseases; targeting TH17 cells is thus a potential treatment for these diseases." (PMID 30451821, 2018). "Th17 cells secrete IL-17 as well as cytokines such as IL-21 and IL-22, and IL-17 can aggravate inflammatory reaction and participate in various autoimmune diseases." (PMID 30151032, 2018). "This subtype is involved in the pathological process of tumors, host defence, infection, autoimmune diseases, and transplant rejection through the secretion of certain cytokines, such as interleukin (IL)-17A, IL-17F, IL-21, IL-22, and IL-6." (PMID 28796055, 2017). "Recent reports suggest that Th17 cells, which produce IL-17A, IL-17 F, IL-21 and IL-22, not only mediate the clearance of pathogens but also promote the progression of tissue inflammation and autoimmune diseases." (PMID 28646856, 2017). "IL-22, responsible for epithelial remodeling and inflammation, plays an important role in a variety of autoimmune diseases, malignant tumors and infectious diseases." (PMID 29262587, 2017). "IL-22 is principally released from Th22 cells and plays a critical role in inflammatory responses that occur in conditions such as autoimmune diseases, infections, and tumors." (PMID 28030850, 2017). "The levels of Th22 and cytokine IL-22 are increased and positively related to inflammatory and autoimmune disorders." (PMID 26261700, 2015). "Several studies indicated that IL-22 production is increased during autoimmune diseases, including rheumatoid arthritis." (PMID 26330334, 2015). "T helper 17 (Th17) cells play a central role in inflammatory and autoimmune diseases via the production of proinflammatory cytokines interleukin- (IL-) 17, IL-17F, and IL-22." (PMID 26792955, 2015). "While a number of studies have shown that IL-22 plays protective roles in host defense against infectious diseases, some studies have shown that IL-22 is involved in the development of autoimmune diseases." (PMID 23577040, 2013). "Mouse-based studies have revealed that Th17 cells co-express IL-22, which plays an important role in antimicrobial responses and autoimmune diseases." (PMID 23798999, 2013). "Because CD4+ T cells play an essential role in the development of autoimmune diseases, we further measured the production of IL-22 by purified CD4+ T cells." (PMID 23527071, 2013). "Previous studies have shown that IL-22 was involved in several inflammatory and autoimmune diseases." (PMID 24312440, 2013). "On the other hand, IL-22 has minor proinflammatory effects, and in some cases such as uveitis, IL-22 seems to play an aggravating role in the pathogenesis of autoimmune disease." (PMID 22312190, 2012).